SUFU (SUFU negative regulator of hedgehog signaling)
Diseases named in the same sentence as SUFU in open-access papers (continued):
Sharing a sentence is not in itself a finding about the gene and the disease.
intraductal papillary mucinous neoplasms (1 paper, 2021). "However, a recent sequence analysis of 315 resected intraductal papillary mucinous neoplasms, which clearly belong to the phenotype of FPC, detected deleterious germline SUFU mutations in a few patients." (PMID 34357098, 2021).
intrauterine growth restriction (1 paper, 2024). "MiR-378a-5p participates in the epigenetic regulation of SUFU gene expression in placental tissue through targeting, thereby influencing intrauterine growth restriction caused by placental insufficiency." (PMID 39176087, 2024).
leprosy (1 paper, 2022). Leprosy is a chronic infectious disease affecting primarily the skin and peripheral nervous system. "One of the credible set SNPs we identify in the leprosy GWAS, rs2274351:T, is located in an active promoter at the 5’ ends of two genes (ACTR1A and SUFU)." (PMID 36121873, 2022).
Macrocephaly (1 paper, 2021). Occipitofrontal (head) circumference greater than 97th centile compared to appropriate, age matched, sex-matched normal standards. "Subject II.1 from family 3 carrying the de novo heterozygous SUFU variant c.479delA shows secondary, nonfamilial macrocephaly as a feature consistent with BCNS." (PMID 33024317, 2021).
malignant mesothelioma (1 paper, 2018). A malignant neoplasm of the pleura or peritoneum, arising from mesothelial cells. "Malignant mesotheliomas can have mutations in PTCH1, Smoothened (SMO), and SUFU genes." (PMID 29498494, 2018).
mental disorder (1 paper, 2024). A disease that has its basis in the disruption of mental process. "Lastly, we identified 3 novel independent loci (PTPRJ, IBDP, and SUFU) that are associated with both kidney function and mental disorders using multi-comics statistical methods such as MTAG and TWAS, which may contribute to a better understanding of the underlying mechanisms." (PMID 38858783, 2024).
mucinous adenocarcinoma (1 paper, 2025). An invasive adenocarcinoma composed of malignant glandular cells which contain intracytoplasmic mucin. "We detected both previously reported (HNF1, SUFU) and unreported (BRCA2, GRIN2A) alterations associated with mucinous adenocarcinoma." (PMID 40302146, 2025).
multiple sclerosis (1 paper, 2022). A progressive autoimmune disorder affecting the central nervous system resulting in demyelination. "Although a more thorough investigation of the joint impact of these mutations on multiple sclerosis is warranted, GLI-1 is a therapeutic target of much interest in cancer, including through its interaction with SUFU, suggesting a starting point for further research." (PMID 35501860, 2022).
osteoporosis (1 paper, 2021). A condition of reduced bone mass, with decreased cortical thickness and a decrease in the number and size of the trabeculae of cancellous bone (but normal chemical composition), resulting in increased fracture incidence. "Lin et al31 confirmed the expression of miR‐874 in rat osteoblasts and found that miR‐874 can target SUFU, thereby promoting the proliferation and differentiation of osteoblasts in osteoporosis rats." (PMID 33713570, 2021).
pancreatic disease (1 paper, 2021). "The present WGS, however, detected potentially pathogenic variants in the ATM, SUFU, DAB1, POLQ, MAP3K3, FGFBP3 and ACAD9 genes that co-segregated with pancreatic disease in single FPC families, and thus might predispose them to the disease." (PMID 34357098, 2021).
sarcoma (1 paper, 2020). A usually aggressive malignant neoplasm of the soft tissue or bone. "The pleomorphic sarcoma with a concurrent IDH1 R132G mutation and a SUFU splice site mutation may indicate that the Hedgehog (Hh) pathway is operant in these cells independent of SHH ligand expression since SUFU is a negative regulator of Hh signaling." (PMID 32570879, 2020).
Sepsis (1 paper, 2023). Sepsis is defined as life-threatening organ dysfunction caused by a dysregulated host response to infection. "We observed that SUFU mRNA was significantly down-regulated in peripheral blood samples of patients with sepsis (GEO data sets GSE54514)." (PMID 37441604, 2023).
serous ovarian cancer (1 paper, 2025). "Except for SUFU, which was associated with poorer survival in serous ovarian cancer, no significant prognostic associations were observed for the target genes across different histological subtypes." (PMID 40565349, 2025).
skin tumors (1 paper, 2013). "Missense or nonsense mutations of SUFU have been noted in GS patients, and a high incidence of KCOT-like jaw lesions and BCC-like skin tumors have been observed in Sufu+/− mice." (PMID 23951062, 2013).
triple-negative breast carcinoma (1 paper, 2022). An invasive breast carcinoma which is negative for expression of estrogen receptor (ER), progesterone receptor (PR), and human epidermal growth factor receptor 2 (HER2). "In addition, hsa-miR-378a-5p was reported to promote apoptosis of triple-negative breast cancer cells by targeting SUFU." (PMID 36104825, 2022).
tumor (87 papers, 2006 to 2026). "Missense mutations were found in another tumor suppressor gene, SUFU, in 1 OS tumor and in the SCOS and SEF samples." (PMID 41514647, 2025). "Lower levels of SuFu protein were linked to high-grade tumors, tumor invasion, late stage, node presence, LNM positivity, PNI positivity, CRC recurrence, and vital status." (PMID 36831076, 2023). "Deletion of the SUFU locus in 25/118 tumours (21%) was associated with marked upregulation of the Patched 2 tumour suppressor (PTCH2)." (PMID 34580349, 2021). "Due to the ‘gate keeper’ role of SUFU in sonic hedgehog pathway, mutations in the SUFU gene were mostly studied in the context of susceptible tumor diseases." (PMID 34589056, 2021). "This mutation impacted the tertiary structure of SUFU, thereby impacting its tumor-suppressor function." (PMID 34298625, 2021). "Extensive NGS analyses revealed a pathogenic germline variant in PTEN and a second variant of the SUFU gene in the tumor DNA." (PMID 32419380, 2020). "Our results from functional characterization of these mutations shed light on SUFU’s role in Hedgehog signaling, tumor progression, and highlight a way in which BCCs can arise." (PMID 28030567, 2016). "Our results show that clinically observed mutations in SUFU have the potential to drive tumor growth and further elucidates SUFU’s role in binding to and suppressing GLI function." (PMID 28030567, 2016). "SUFU acts as a classic tumor suppressor gene, with mutations leading to the inability of SUFU to transport GLI1 out of the nucleus to the cytoplasm, thereby resulting in aberrant activation of HH signaling in MB." (PMID 23826113, 2013). "We observed other markedly under-expressed genes (P<0.05) included tumour-suppressor candidates that negatively regulate the Hh pathway (SUFU, GAS1, RAB23) and genes encoding inhibitory proteins (HHIP, HHAT)." (PMID 22361633, 2012). "Several mechanisms have been described that lead to the activation of the Hh signaling pathway in tumor cells, such as activating point mutations of Smo or inactivating point mutations in Ptch1 or SUFU." (PMID 21235817, 2011). "Furthermore, we characterize mutations found in tumor samples that define an expanded SUFU-affinity-modulating region." (PMID 35831023, 2022). "Moreover, the ROC1 and SUFU expression levels were associated with the tumor pathological grade, whereas the ROC1 expression was inversely associated with the SUFU expression (P = 0.014) but positively associated with the Gli2 expression (P = 0.001)." (PMID 33499884, 2021). "Additionally, an analysis of the pathological characteristics of GC based on the ATGC data showed that the expression levels of SUFU and miRNA-150 are associated with tumor differentiation." (PMID 33848981, 2021). "Since E376K appeared in two independent early-stage BCCs, our data suggests we may be able to predict which SUFU variants would promote tumor growth through similar side chain interactions." (PMID 28030567, 2016). "In addition, both the miRNA-150 and SUFU levels were associated with tumor differentiation." (PMID 33848981, 2021). "Similarly, tumours with an activating mutation in the HH pathway downstream of SMO, such as SUFU loss, or tumours that develop resistance to SMO inhibitors, may be responsive to GANT61 or similar inhibitors that target GLI1." (PMID 30068568, 2018). "While most studies on HHI resistance have focused on tumor‐intrinsic mechanisms, including canonical mutations in SMO, SUFU, or GLI2 that reactivate HH signaling, these alterations alone do not fully explain clinical variability in treatment response." (PMID 41543881, 2026). "Genomic analysis of tumor samples from 1113 PM patients revealed mutations in HP genes (such as PTCH1 and SUFU), though these mutations were rare (PTCH1 at 1.2%, SUFU at 0.8%)." (PMID 40904706, 2025).
tumor (continued). "Similar to GSK3-beta, which regulates the activity of GLIs and beta-catenin, SUFU tumor suppressor, a well-known negative regulator of the Hedgehog pathway, inhibits both Hedgehog and Wnt through the interaction with GLIs and beta-catenin as well." (PMID 38474826, 2024). "An earlier study demonstrated that SuFu expression is correlated with tumor invasion depth and tumor diameter." (PMID 36831076, 2023). "The findings show that SuFu is downregulated in CRC tumor tissues at both the mRNA and protein levels with predominant nucleo-cytoplasmic localization." (PMID 36831076, 2023). "A cell line-based study showed that the overexpression of SuFu had a regulatory effect on colon cancer cells, and inhibited cell growth and tumor formation." (PMID 36831076, 2023). "SuFu was downregulated in a higher number of tumor samples (n = 62, 63.2%) than adjacent normal tissues and was predominantly localized in the nucleo-cytoplasm, followed by the nucleus and the cytoplasm." (PMID 36831076, 2023). "SuFu—a key tumor-suppressor gene of the hedgehog signaling pathway—has been linked to various cancers." (PMID 36831076, 2023). "In the present study, SuFu mRNA and protein expression were evaluated in histopathologically confirmed tumor tissues and adjacent normal tissues." (PMID 36831076, 2023). "IHC analysis revealed that SuFu was downregulated in 63.3% of the malignant tumor tissues relative to adjacent normal tissue samples." (PMID 36831076, 2023). "Altogether, our findings demonstrate that SNEP1 acts as a novel feedback regulator of Hh signaling by destabilizing SuFu and promoting tumor growth and anti-Hh resistance." (PMID 33608498, 2021). "This includes overexpression of HH ligand in tumor and tumor microenvironment (TME), loss of function mutation in PTCH1 and SUFU, GLI2 amplifications, and gain of function mutation in SMO." (PMID 34831357, 2021). "The repressors of the pathway (SUFU and PTCH1) are considered tumor suppressors, as their loss of function upregulates the Hh/GLI signaling activity to drive tumorigenesis." (PMID 34298625, 2021). "An important finding of our study was deletion of the SUFU locus on chromosome 10q24.32 in 21% of tumours." (PMID 34580349, 2021). "Here, we demonstrate that a well-known tumor suppressor, Suppressor of Fused (SUFU), is downregulated by SPOP." (PMID 34021128, 2021). "Our cell viability assay also demonstrated that knockdown of SUFU expression was able to partially restore tumor cell growth upon ROC1 knockdown in 5637 and T24 cells." (PMID 33499884, 2021). "A striking novel finding in RNA-sequencing expression data of tumours with SUFU locus deletion was the downregulation of T-cell and antigen-presenting cell genes." (PMID 34580349, 2021). "The tumor suppressor SuFu inhibits Hh signaling by preventing the nuclear translocation of Gli and suppressing cell proliferation." (PMID 33608498, 2021). "In our study, we first identified SUFU as a tumor suppressor in ccRCC through the use of bioinformatics analysis and experimental verification." (PMID 34021128, 2021). "Hippo pathway activation was observed in more than 50% of mesothelioma tumours while Hedgehog pathway activation, as SUFU deletion, was seen in 21% of the tumours." (PMID 34580349, 2021). "The results of further IHC studies of these three molecules indicated that the PKA and SUFU protein were mainly localized in the cytoplasm of tumor cells, while the GLI1 protein was mainly localized in the cytoplasm and nucleus." (PMID 31519191, 2019). "Dysregulation of the Hh pathway observed in MB and other tumours can be caused by ligand-independent events, such as genetic mutations of pathway components (PTCH, SMO, SuFu, REN, GLI1/GLI2 amplification) or ligand-dependent mechanisms of activation." (PMID 30699938, 2019).
tumor (continued). "Exosomes released by osteoclasts can stimulate tumor proliferation, as miR-378 promotes tumor growth, angiogenesis, and tumor cell survival through the repression of tumor suppressors SuFu and Fus-1." (PMID 29642618, 2018). "The relevance of Itch-dependent ubiquitylation of SuFu in the control of tumour growth was also validated in primary MB cells derived from Ptch+/− mice." (PMID 29515120, 2018). "For example, osteoclasts secrete exosomes containing miRNAs such as miR-378 which promotes tumour growth, angiogenesis and tumour cell survival through the repression of tumour suppressors SuFu and Fus-1." (PMID 27761364, 2016). "Recently, miR-378a was reported to regulate tumor angiogenesis mainly via inhibition of tumor suppressors SuFu and Fus-1." (PMID 26839547, 2015). "In these types of cancer, miR-378 seemed to be an oncogene, and enhanced tumor cell survival, promoted tumor growth and metastasis in some tumors via regulation of the target genes SuFu, Fus-1, HMOX1, ESRRG and GABPA." (PMID 24555885, 2014). "Earlyclinical trials of SHH pathway inhibitors are underway, although acquired resistancehas been reported and tumours with downstream pathway mutations (e.g. GLI2, SUFU)are predicted to be insensitive to their action." (PMID 24252690, 2013). "Although alterations in SHH pathway genes (e.g.PTCH1, SUFU) are observed in many of these tumours,high throughput genomic analyses have identified few other recurringmutations." (PMID 24252690, 2013). "Moreover, anti-apoptotic BCL2 proteins promote hedgehog/Gli signaling by enhancing the turnover of a Gli antagonist, SUFU tumor suppressor to inhibit Gli-SUFU interaction, thus increasing the expression of Gli target genes such as BCL2." (PMID 41353440, 2025). "However, the precise role of suppressor of fused (SUFU), one of the two well-recognized tumor suppressor genes in the SHH pathway, in addition to Patched1 (PTCH1), is not completely understood." (PMID 38358805, 2024). "SuFu was downregulated in CRC tumor tissues at both the mRNA and protein levels." (PMID 36831076, 2023). "Moreover, it has been shown that antiapoptotic BCL2 proteins have a role in promoting hedgehog/GLI signaling by enhancing the turnover of a GLI antagonist, SUFU tumor suppressor." (PMID 34282785, 2021). "Given the importance of SUFU as a tumor suppressor, we investigated whether other miRNAs would also target SUFU mRNA." (PMID 33848981, 2021). "Patient SJMB335 had a somatic SUFU missense mutation, but clonal evolution analysis did not provide evidence for an SUFU-associated tumor as a result of low mutation frequency." (PMID 31609649, 2020). "Indeed, it has been identified as a tumour suppressor that limits GLI1 oncogenic properties, and enforces SuFu tumour suppressor functions, thus keeping the Hh pathway off." (PMID 30699938, 2019). "SUFU plays a tumor-suppressive role by maintaining the inactivity of GLI transcription factors." (PMID 31519191, 2019). "LEE found that miR378 could promote cell survival, tumor growth, and angiogenesis by targeting SuFu and Fus-1 expression." (PMID 29686962, 2018). "Fourteen of the mutated genes in this tumor are involved in metabolism (endogenous molecules as well as drugs), small molecule biochemistry, and cancer: AATF, ATF71P, CRIPAK, CROCC, CYP2A6, DOCK5, GPAT2, KRTAP4–9, LSM14A, MUC2, MYO1F, RHOQ, SUFU, and UTRN." (PMID 29259192, 2017). "Also down-regulated was suppressor of fused (SUFU), which is considered a tumour suppressor gene because of its inhibitory influence on the hedgehog pathway." (PMID 25864518, 2015). "In addition to the targets that we identified by RNA sequencing, miR-378a-5p has been shown to be involved in tumorigenesis and tumor maintenance by regulating SUFU, TUSC2, TOB2, GABPA and ESRRg." (PMID 24651706, 2014).